MTA1 (metastasis associated 1)
Diseases named in the same sentence as MTA1 in open-access papers (continued):
Sharing a sentence is not in itself a finding about the gene and the disease.
tumor (continued). "Western blot analysis of xenograft tumor tissues confirmed a strong MTA1, Cyclin D1 and Notch 2 downregulation upon treatment with compounds compared to control vehicle-treated tissues." (PMID 33255879, 2020). "Metastasis‐associated gene 1 (MTA1) has identified as an oncogene in several human tumours, and aberrant MTA1 expression has been related to the EMT regulation." (PMID 32187849, 2020). "Immunohistochemical analysis of the tumor tissues showed high MTA1 expression in control mice and significant MTA1 downregulation in mice treated with all the compounds." (PMID 33255879, 2020). "We also explore the role of MTA1 in the gem-induced tumor toxicity effect in vitro and in vivo using small interfere RNA (siRNA) and the adenovirus stable knockdown system." (PMID 33282725, 2020). "Studies have shown that high expression of MTA1 is usually discovered in patients with lung infiltrating adenocarcinoma, which is statistically relevant to tumor sizes, lymph node metastasis and microvascular density." (PMID 32410569, 2020). "Further, we find that knockdown of MTA1 strengthens the gemcitabine-mediated tumor growth inhibition effect in vivo, through reversion of the EMT process and inhibition of the autophagy process." (PMID 33282725, 2020). "MTA1 mediated the tumor cell migration and invasion in cultured cells through the regulation of E-cadherin, MPP2, and MPP9 via the NF-κB pathway." (PMID 33059651, 2020). "We previously validated presence of cytoplasmic MTA1 and its positive correlation with tumor progression." (PMID 32901005, 2020). "Vivo experiments revealed that miR-543 promoted cells proliferation and angiogenesis in tumor tissues via modulating MTA1." (PMID 32410569, 2020). "In the following experiments, we found that down-regulation of MTA1 enhances the tumor growth inhibition effect from GEM in MCF-7 cells in vitro (Figure 2A4) through enhancing cell apoptosis and ros-reaction levels." (PMID 33282725, 2020). "The results showed that miR-543 or MTA1 overexpression promoted the growth of tumor with increase of tumor volume and weight (p < 0.05)." (PMID 32410569, 2020). "Compared with the miR-543 mimic group, tumor volume and weight were reversed in the miR-543 mimic+MTA1 siRNA group (p < 0.05)." (PMID 32410569, 2020). "The data indicated miR-543 overexpression increased tumor microvascular density by upregulating MTA1." (PMID 32410569, 2020). "MTA1 is over-expressed in many cancers, including BC, and correlates with tumor metastasis and progression in human BC and transgenic mouse models." (PMID 30782165, 2019). "This is the first report showing that BC exosomes contain MTA1 and can transfer it to other cells resulting in changes to hypoxia and estrogen receptor signaling in the tumor microenvironment." (PMID 30782165, 2019). "We extracted data on demographics, treatment and primary malignancy and examined available tumor samples for MTA-1 and ezrin using immunohistochemistry (IHC)." (PMID 32039013, 2019). "We have previously shown that resveratrol and pterostilbene specifically inhibit MTA1 and MTA1-guided tumor promoting signaling in PCa." (PMID 31487842, 2019). "Our previous study found that MTA1 was upregulated in tumor cells treated with chemotherapy drugs such as cisplatin, 5-fluorouracil, and pacitaxel." (PMID 30596107, 2018). "The same study correlated miR-30c-2* and MTA-1 expression with tumor stage and lymph node metastases." (PMID 30563114, 2018). "Noticeably, expression of MTA1 increased, especially in tumor periphery with dramatical upregulation after TACE." (PMID 28589145, 2017). "Positive HIF-1a staining was observed in the tumor cells after TACE, and its localization was similar to MTA1, which clustered at the periphery of substantial central necrosis and scattered at the areas near focal necrosis of tumor peripheral zone." (PMID 28589145, 2017).
tumor (continued). "One month after TACE treatment, tumor tissues exhibited extensive necrosis and expression of MTA1 increased dramatically in residual tumor cells which were distributed in the border of necrotic tumor regions and the tissues of tumor periphery." (PMID 28589145, 2017). "Recently, it is indicated that elevated expression levels of MTA1 in several tumor types, such as gastric, breast, colorectal, and esophageal carcinomas, appear to increase cell motility, potentiate growth, and enhance metastases." (PMID 28589145, 2017). "MiR-661 was firstly found in breast cancer as a tumor suppressor which inhibits proliferation, motility and invasion of tumor cells through suppression of a metastasis-related protein MTA1." (PMID 28716024, 2017). "And according to tumor type, we investigated MTA1 expression in patients with gastrointestinal cancers (GI cancers) or EC." (PMID 28570554, 2017). "Strongly positive MTA1 staining was detected predominantly in the border of necrotic tumor regions and tumor periphery after TACE treatment, compared with most of extensively weak expression before TACE treatment." (PMID 28589145, 2017). "MTA1 overexpression correlated significantly with higher tumor grade (grades 1 and 2 vs grade 3, P = 0.009)." (PMID 29254284, 2017). "Our study provides preclinical evidence that Pter/SAHA combination treatment inhibits MTA1/HIF‐1α tumor‐promoting signaling in PCa." (PMID 29024573, 2017). "To explore the potential clinical significance of wk-MTA1dE4, we assessed the percentage of wk-MTA1dE4 overexpression in woodchuck HCCs and further correlated the expression levels of the total wk-MTA1 and wk-MTA1dE4 with different tumor characteristics." (PMID 27323415, 2016). "Cancer spread has been linked to expression of EBV LMP2A on the cell surface as a result of increased expression of the metastatic tumor antigen 1 (MTA1), which plays an important role in tumor recurrence and metastasis." (PMID 27231932, 2016). "In the present study, we evaluated the correlation between MTA1 level and clinical-pathological factors such as tumor size, grade, stage and metastasis to lymph nodes." (PMID 26878004, 2016). "MTA1 increases the expression of histone deacetylase-1 and causes deacetylation of HIF-1α, which is involved in tumor angiogenesis." (PMID 26878004, 2016). "MTA1 has been shown to be overexpressed in various human cancers and involved in tumor invasion, higher metastatic potential and advanced clinical stage." (PMID 26878004, 2016). "We observed a notably high expression level of wk-MTA1dE4, particularly in tumor tissues, accounting for approximately 50% of the total wk-MTA1." (PMID 27323415, 2016). "Immunohistochemical analysis showed that tumors from leptin-treated mice exhibited higher number of tumor cells showing increased expression of MTA1, Wnt1, β-catenin and cyclin D1 as compared to tumors from vehicle-treated group." (PMID 26036628, 2015). "The expression patterns of E-cadherin and MTA1 in stained tumor cells were membranous and nuclear, respectively." (PMID 25609245, 2015). "In univariate analysis, tumor differentiation (p = 0.008), local progression (p = 0.001), lymph node metastasis (p < 0.001), clinical stage (p < 0.001), MTA1 and EpCAM high expression (p < 0.001) significantly predicted unfavorable overall survival." (PMID 26698569, 2015). "Positive signals of EIF5A2 were predominantly located in the cytoplasm and nucleus of tumor cells, while MTA1 signals were mainly localized in the nucleus of tumor cells." (PMID 25793713, 2015). "Tumors from HNK+leptin treatment group showed very low percentage of tumor cells showing expression of MTA1, Wnt1, β-catenin and cyclin D1 providing physiological relevance to our in vitro findings." (PMID 26036628, 2015). "Higher percentage of tumor cells showed increased expression of MTA1, β-catenin and cyclin D1 in HFD group as compared to ND group." (PMID 26036628, 2015).
tumor (continued). "MiR-30c directly inhibits MTA-1 expression and functions as a tumour suppressor via the miR-30c-MTA-1 signalling pathway." (PMID 24595016, 2014). "Although the contribution of MTA1 to the promotion of tumor invasion and metastasis has been well characterized, a role for this protein in other malignances, such as cancer differentiation, has remained largely unexplored." (PMID 24970816, 2014). "Our previous studies have found that miR-30c targets MTA-1, which is highly expressed in EC and functions as tumour suppressor in EC cell lines." (PMID 24595016, 2014). "MTA1 is highly upregulated in several types of aggressive tumours and is therefore a possible target for cancer therapy." (PMID 25352341, 2014). "We previously determined that miR-30c targets MTA-1, which is overexpressed in EC and which acts as an oncogene in many human tumours." (PMID 24595016, 2014). "MTA1 overexpression is correlated with clinicopathological parameters that characterize tumor aggressiveness: lymph node metastasis, high tumor grades, and angiogenesis in various cancers." (PMID 23469203, 2013). "We have previously shown that endogenous levels of MTA1 promote tumor development in a subcutaneous model of PCa." (PMID 23469203, 2013). "These divergent findings suggest that the effect of MTA1 on tumor cell growth and cell cycle progression are cell dependent." (PMID 23941622, 2013). "Compared with control, the average tumor volume in mice injected with MTA1 depleted C666-1 or CNE1 cells was markedly reduced by more than 60% (p < 0.01)." (PMID 23941622, 2013). "We have also shown that MTA1 knockdown cells had suppressed invasion and angiogenic activity in vitro, and delayed tumor formation and development in subcutaneous xenografts." (PMID 23469203, 2013). "The results demonstrated that the number of Ki-67 positive cells was significantly decreased in tumor nodules originating from MTA1 depleted cells, compared to control cells." (PMID 23941622, 2013). "MTA1, the founding member of the MTA family proteins that include MTA1, MTA2 and MTA3, was initially identified as a metastasis-associated tumor gene." (PMID 23286669, 2013). "MTA1 expression was assessed using immunohistochemistry in paraffin-embedded tumor specimens from 208 untreated NPC patients." (PMID 22537306, 2012). "All of these studies have indicated that MTA1 plays an important role in tumor cell invasion and metastasis." (PMID 23227138, 2012). "It's indicated that MTA1 gene involved in the critical molecule mechanism of tumor infiltration and metastasis." (PMID 21595884, 2011). "After silencing of MTA1 gene, we investigated the alteration of tumor cells invasiveness using Boyden chamber assay mentioned in Albini's literature." (PMID 21595884, 2011). "Currently, researches that involved the gene such as MTA1, which were related to tumor metastasis, revealed that the expression level was closely related to the metastatic ability." (PMID 21595884, 2011). "We further analysed the expression of MTA1 in murine tissues and tumour cell lines since MTA1 is highly conserved in humans and mouse demonstrating 96% similarity at the protein level." (PMID 18949081, 2008). "Our results demonstrate that high levels of MTA1 transcripts are expressed in all murine tumour cell lines tested, compared with the low levels expressed in normal mouse tissues." (PMID 18949081, 2008). "Most of the tissues expressed MTA1 transcripts at low levels, whereas high levels of expression were observed in all tumour cell lines." (PMID 18949081, 2008). "We also analysed the expression pattern of the murine MTA1 gene in different tissues and in tumour cell lines." (PMID 18949081, 2008). "Among these, we identified MTA1 and our data extends previously published studies regarding its over-expression in aggressive tumours." (PMID 18949081, 2008). "The relative overexpression of MTA1 mRNA (tumour/normal ratio ≥ 2) was observed in 16 out of 47 (34.0%) oesophageal carcinomas." (PMID 10206283, 1999).
tumor (continued). "However, further studies are required to elucidate the precise mechanisms by which MTA1 contributes to tumor progression." (PMID 40565190, 2025). "As a transcriptional co-regulator, MTA1 is involved in tumor metastasis and progression." (PMID 40565190, 2025). "We found that in a microarray study of 60 tissue samples, MTA1 mRNA expression was significantly higher in primary tumor tissue (n = 33) compared to normal urothelium (n = 14), and that the expression was even higher in cases involving muscle invasion (n = 13)." (PMID 40351767, 2025). "Positive PROX1 and high MTA1 expressions were significantly associated with large tumor sizes (T3 & T4), presence of nodal and distant metastasis, advanced TNM clinical stage (III + IV), and presence of tumor recurrence (P values were ≤ 0.05)." (PMID 40660330, 2025). "Additionally, in human breast cancer, stable HIF-1α induced by LSD1 interacts synergistically with CBP and MTA1 to promote tumor angiogenesis induced by VEGF, providing continuous oxygen and nutrition for tumor growth." (PMID 39629133, 2024). "The recruitment of MTA1 to these tumor suppressors was attenuated when MTA1 was knocked down." (PMID 39154024, 2024). "Further investigations are warranted to determine how MTA1-tumor heterogeneity impacts the effectiveness of treatment and whether target phospho-protein levels can be used as reliable biomarkers for combinatorial treatment response." (PMID 38611022, 2024). "The analysis of MTA1 and its exon 4-excluded form (MTA1dE4), the most abundant spliced variant of MTA1, showed that MTA1dE4 overexpression in tumor, but not MTA1, was associated with early recurrence." (PMID 36689059, 2023). "The protein MTA1 has already been investigated as a potential prognostic factor in other gynecologic tumors, such as ovarian, cervical, and endometrial carcinoma, and correlated with tumor progression and metastases." (PMID 36689059, 2023). "FTO exerted a tumor suppressive role by inhibiting MTA1 expression in an m6A-dependent manner." (PMID 37391814, 2023). "Furthermore, when labeling the T cells with the immune markers Ifng or Tigit, the interaction between tumor cells and both T cells expressing Ifng or T cells expressing the immune checkpoint Tigit was significantly decreased in the MTA1-overexpressing group." (PMID 35350571, 2022). "In summary, these data support our overall hypothesis that SMYD3 cooperates with the NuRD (MTA1/MTA2) complex to inhibit expression of a series of tumor suppressor genes, leading to tumor progression." (PMID 36575438, 2022). "Mechanistically, we described that the chemokines and cytokines downregulated by MTA1 in cancer cells may result in decreased macrophages in the tumor microenvironment." (PMID 35350571, 2022). "Furthermore, the RUNX2/NuRD(MTA1)/CRL4B complex contributed to the epigenetic silencing of tumor suppressors." (PMID 35534547, 2022). "However, the addition of macrophages enhanced the interaction between T cells and MTA1-overexpressing tumor cells, eliminating the difference between the interaction of T cells with MTA1-high and MTA1-low cancer cells." (PMID 35350571, 2022). "In particular, the downregulation of CCL2 was significantly associated with the absence of macrophages in the MTA1-high tumor group." (PMID 35350571, 2022). "MTA1 is widely upregulated as a key factor in tumor progression in various types of cancers." (PMID 34218271, 2021). "However, we observed that the variability of tumor burdens (including size and number) among mice in the same group is too large to investigate the additive effect of MTA1 or MTA1dE4 on accelerating tumorigenesis." (PMID 34502289, 2021). "Furthermore, histologic examination showed that FTO overexpression reduced MTA1 expression in tumor tissue." (PMID 34218271, 2021). "Moreover, IGF2BP2 expression was positively correlated with MTA1 expression in 78 CRC tumor tissues from the independent SYSUCC cohort." (PMID 34218271, 2021).
tumor (continued). "In NSCLC, the overexpression of MTA1 could lead to tumor growth and microvessel density (MVD) increase by inducing other relevant oncogenes expression." (PMID 32410569, 2020). "Furthermore, we tested the long-term tumor growth inhibition effect of combining treatment of MTA1 knockdown and GEM." (PMID 33282725, 2020). "These revealed that miR-543 overexpression promoted tumor growth via regulating MTA1." (PMID 32410569, 2020). "We illustrated the correlations of MTA1 with thirty reported splicing factors, with MTA1-GAPDH correlation as an irrelevant control, supporting that MTA1-RNA association-related posttranscriptional regulation is linked to tumor initiation." (PMID 32901005, 2020). "In addition, previous studies explore that MTA1 is closely related to tumor angiogenesis, including NSCLC." (PMID 32410569, 2020). "In addition, there are other genes related to tumour metastasis, such as MTA1, and the FAKT c‐Src gene, which are also involved in the signal transduction process of tumour cells and affect their metastasis." (PMID 31957271, 2020). "Abnormal activation of JMJD5 and MTA1 contributes to tumor survival, growth, and metastasis." (PMID 32678829, 2020). "In recent years, MTA1 has been revealed to promote tumor progression and distant metastasis." (PMID 32410569, 2020). "Interestingly, our data show that, MTA1-loaded exosomes successfully enhanced the GEM-mediated tumor growth inhibition effect." (PMID 33282725, 2020). "The results were further confirmed in vivo in a follow-up study, and it was shown that the MTA1-mediated tumor progression was, in part, due to PTEN inactivation and that resveratrol could acetylate and reactivate PTEN." (PMID 30781847, 2019). "Our results support that MTA1 is positively correlated with tumor metastasis." (PMID 30596107, 2018). "Similarly, the presence of MTA1 in NuRD complexes correlates with metastatic growth of human tumor tissue and MTA3 with normal growth and differentiation." (PMID 29490265, 2018). "Tumor tissues expressing MTA1 show deeper invasion into the lymphatic network under the mucosa." (PMID 28570554, 2017). "Results from our ChIP-Seq analysis identified oncogenic c-Myc, Cyclin D1, Ets2, Akt1 and Notch2, pro-inflammatory Hsp90, pro-lymphangiogenic VEGF-C, and pro-apoptotic p27 as novel transcriptional targets of MTA1, revealing its ability to simultaneously activate multiple tumor-promoting pathways." (PMID 26943043, 2016). "In tumor cells, wk-MTA1 staining was much denser in the nucleus than in the cytoplasm." (PMID 27323415, 2016). "Therefore, in this study we attempted to evaluate MTA1 expression in SGTs by using an immunohistochemical approach to establish correlation with tumor grade and stage and to determine prognostic value." (PMID 26878004, 2016). "Although MTA1 overexpression was seen in patients with advanced tumor size and clinical stage, the difference between groups was not statistically significant, which may be because of the low number of cases in our study." (PMID 26878004, 2016). "Importantly, pterostilbene both as dietary supplementation and interventional daily injections, through targeting MTA1 and its tumor promoting network, inhibited inflammation, proliferation and angiogenesis and induced apoptosis." (PMID 26943043, 2016). "Restoration of MTA1 expression resulted in significantly increased tumor sizes in Hep3B-ERα/MTA1." (PMID 26503703, 2015). "Overexpression of MTA1 also significantly correlates with large tumor size." (PMID 26503703, 2015). "Some reports elucidating EpCAM-regulated downstream signaling molecules, such as E-cadherin and Wnt/β-catenin may help explain our founding on MTA1 and EpCAM modulation to promote tumor invasion and migration." (PMID 26698569, 2015). "Accumulating evidence suggests that MTA1 may promote tumorigenesis and tumor aggressiveness through changing the expression of cell adhesion molecules." (PMID 26698569, 2015).